CFAP74 (cilia and flagella associated protein 74)
Description:
As part of the central apparatus of the cilium axoneme may play a role in cilium movement. May play an important role in sperm architecture and function.
Synonyms: C1orf222; KIAA1751; FLJ45476; CILD49
Tractability: No criterion of Open Targets' tractability assessment is met for any kind of drug.
Gene: Protein-coding gene on chromosome 1 (1,921,951 to 2,003,837, reverse strand). Ensembl gene ENSG00000142609.
Subcellular location: Cytoplasm, cytoskeleton, cilium axoneme; Cytoplasm, cytoskeleton, flagellum axoneme
Gene Ontology:
Molecular function: protein binding
Biological process: axoneme assembly
Cellular component: cytoplasm; nucleus; sperm flagellum; axoneme
Genetic constraint (gnomAD): Loss-of-function variants: 115 observed, 168.04 expected, observed/expected ratio (o/e) 0.68, 90% interval 0.59 to 0.8. The upper end of that interval is the gene's LOEUF score, 0.8, which puts it in group 3 of 6, group 1 being the genes least tolerant of losing a copy. Missense variants: 2,117 observed, 2,109.3 expected, observed/expected ratio (o/e) 1, 90% interval 0.97 to 1.04. Synonymous variants: 929 observed, 896.1 expected, observed/expected ratio (o/e) 1.04, 90% interval 0.98 to 1.09.
Gene-disease validity (ClinGen):
ClinGen rates the evidence that CFAP74 causes each of these diseases.
ciliary dyskinesia, primary, 49, without situs inversus (autosomal recessive): Moderate.
Homologues: Orthologues: chimpanzee CFAP74 (92% identical), dog CFAP74 (72% identical), rat Cfap74 (71% identical), mouse Cfap74 (70% identical), pig CFAP74 (64% identical), guinea pig CFAP74 (61% identical), tropical clawed frog cfap74 (46% identical), zebrafish cfap74 (33% identical).
Diseases named in the same sentence as CFAP74 in open-access papers:
CFAP74 is named in the same sentence as 2 diseases in open-access papers, as found by Europe PMC text mining. Sharing a sentence is not in itself a finding about the gene and the disease. The quoted sentences say what the papers report.
Age-related cataract (1 paper, 2021). A type of cataract (opacification of the lens) that forms during the course of aging. "Some of these genes associated with age-related cataracts include FRMD4B, NAALADL2, LOC105377670, LINC00968, LOC101929415, CTNNA3, LOC107984170, PRCP, and ZNF423, whereas others with a reduced risk include CFAP74, ACSL1, LOC101927668, LOC105369844." (PMID 34299682, 2021).
CFAP74 also shares sentences with these, for which no sentence is quoted: oligospermia (1 paper).